PIGU (phosphatidylinositol glycan anchor biosynthesis class U)
Description:
Component of the glycosylphosphatidylinositol-anchor (GPI-anchor) transamidase (GPI-T) complex that catalyzes the formation of the linkage between a proprotein and a GPI-anchor and participates in GPI anchored protein biosynthesis. Binds the lipid portion of GPI-anchor. May act as an organizer in the transmembrane layer to recruit other subunits, and thus is essential for assembly of the complex.
Synonyms: CDC91L1; bA346K17.2; GAB1; PIG-U; GPIBD21; NEDBSS
Tractability: Small molecule: a structure with a bound ligand is known. Antibody: its Gene Ontology location is reachable by antibodies, with high confidence; UniProt predicts a signal peptide or a membrane-spanning region. PROTAC: ubiquitination databases record sites on it; its protein half-life has been measured.
Gene: Protein-coding gene on chromosome 20 (34,560,542 to 34,698,790, reverse strand). Ensembl gene ENSG00000101464.
Subcellular location: Endoplasmic reticulum membrane
Subcellular location (Human Protein Atlas): Nucleoplasm; Cytosol
Pathways (Reactome):
Metabolism of proteins: Attachment of GPI anchor to uPAR
Gene Ontology:
Molecular function: GPI anchor binding; protein binding
Biological process: attachment of GPI anchor to protein; GPI anchor biosynthetic process; GPI anchored protein biosynthesis; regulation of receptor signaling pathway via JAK-STAT
Cellular component: GPI-anchor transamidase complex; membrane; plasma membrane; endoplasmic reticulum membrane
Genetic constraint (gnomAD): Loss-of-function variants: 19 observed, 41.33 expected, observed/expected ratio (o/e) 0.46, 90% interval 0.32 to 0.68. The upper end of that interval is the gene's LOEUF score, 0.68, which puts it in group 2 of 6, group 1 being the genes least tolerant of losing a copy. Missense variants: 453 observed, 481.47 expected, observed/expected ratio (o/e) 0.94, 90% interval 0.87 to 1.02. Synonymous variants: 204 observed, 185.43 expected, observed/expected ratio (o/e) 1.1, 90% interval 0.98 to 1.24.
Gene-disease validity (ClinGen):
ClinGen rates the evidence that PIGU causes each of these diseases.
glycosylphosphatidylinositol biosynthesis defect 21 (autosomal recessive): Limited. An autosomal recessive disorder characterized by global developmental delay, severe-to-profound intellectual disability, muscular hypotonia, seizures, brain anomalies, including thin corpus callosum and cerebellar atrophy, scoliosis, and mild facial dysmorphism.
Homologues: Orthologues: chimpanzee PIGU (100% identical), dog PIGU (99% identical), rabbit PIGU (98% identical), pig PIGU (97% identical), mouse Pigu (97% identical), rat Pigu (97% identical), guinea pig PIGU (97% identical), macaque PIGU (95% identical), tropical clawed frog pigu (78% identical), zebrafish pigu (76% identical), Drosophila melanogaster PIG-U (37% identical), Caenorhabditis elegans pigu-1 (24% identical).
Diseases named in the same sentence as PIGU in open-access papers:
PIGU is named in the same sentence as 18 diseases in open-access papers, as found by Europe PMC text mining. Sharing a sentence is not in itself a finding about the gene and the disease. The quoted sentences say what the papers report.
bladder cancer (9 papers, 2006 to 2024). "PIGT’s counterpart, PIGU, has been shown to be increased in bladder cancer, and more importantly, study showed that overexpressing PIGU malignantly transformed NIH3T3 cells." (PMID 38169393, 2024). "Two proteins of the glycosylphosphatidylinositol (GPI) anchoring system, PIGU and PIGC, were top genes with respect to significant monotonic expression; of these, PIGU is a known bladder cancer oncogene." (PMID 31277598, 2019). "Other cancer-related genes at 20q include E2F1, which is specifically targeted by hrHPV-mediated degradation of pRb, PIGU, which may play a role in cell cycle control and was identified as an oncogene in bladder cancer, and DNMT3B, a de novo DNA methyl transferase." (PMID 19486517, 2009). "Previous studies have demonstrated that other PIG class members, such as PIGU and PIGT, are oncogenes in either human bladder cancer or breast cancer, respectively." (PMID 24483146, 2014).
breast carcinoma (4 papers, 2014 to 2024). "Surprisingly, In multiple microscopic views, the expression of GPAA1 and PIGU in breast cancer cells was negatively correlated with the expression of CD8 molecules in neighboring lymphocytes." (PMID 39015576, 2024). "We also found that GPAA1 and PIGU are highly amplified in breast cancer cell lines, and inhibiting the expression of PIGU has a negative impact on cell proliferation." (PMID 39015576, 2024). "The infiltration of CD8+T cells in breast cancer exhibits a negative correlation with the expression levels of GPAA1 and PIGU." (PMID 39015576, 2024).
gastric cancer (4 papers, 2019 to 2025). A primary or metastatic malignant neoplasm involving the stomach. "However, in pancreatic cancer, a lower expression of PIGU is associated with a worse prognosis, whereas higher expression of PIGU in liver cancer is linked to poorer outcomes, a pattern that is also observed in gastric cancer." (PMID 41542087, 2025). "We further investigated the potential target genes or proteins influenced by FAM117A and PIGU in the development of gastric cancer cells." (PMID 41542087, 2025). "Our study has identified the potential regulatory roles of FAM117A and PIGU in gastric cancer development through multi-omics analysis and cellular experiments, but several limitations should be noted." (PMID 41542087, 2025). "Overexpression of FAM117A and knockdown of PIGU significantly inhibited the proliferation of gastric cancer cells, with cell activity decreasing markedly over time." (PMID 41542087, 2025). "Both FAM117A and PIGU are pivotal genes in the regulation of gastric cancer and represent important targets in the gastric cancer continuum." (PMID 41542087, 2025). "In breast, bladder, and gastric cancer, the high expression of other GPI-anchor biosynthesis glycogenes, such as PIGU, PIGT, and PIGX, is associated with oncogenesis, poor prognosis, and tumorigenesis." (PMID 34540372, 2021). "Database analysis indicated that low FAM117A expression and high PIGU expression may promote gastric cancer progression." (PMID 41542087, 2025). "Among the previous findings, this study identified FAM117A and PIGU as crucial genes involved in the gastric cancer continuum, suggesting that dysregulation of cell proliferation and alterations in cell adhesion molecule (CAM) expression contribute significantly to gastric cancer development." (PMID 41542087, 2025). "Therefore, FAM117A and PIGU may play roles in regulating the occurrence and progression of gastric cancer." (PMID 41542087, 2025).
malignant melanoma (2 papers, 2017 to 2022). "The reported candidate gene PIGU is the gene most proximal to the lead SNP rs910873 and maybe a novel candidate gene involved in melanoma." (PMID 35079000, 2022). "In conclusion, while we cannot rule out PIGU as a candidate gene for malignant melanoma, these findings point to an alternate, and possibly more biologically relevant candidate, ASIP." (PMID 35079000, 2022).
Burkitt lymphoma (1 paper, 2012). A rare form of malignant mature B-cell non-Hodgkin lymphoma. "We find for instance exonic deletions in the potential oncogene PIGU, and intronic deletions in PRKCA, which is overexpressed in some Burkitt's lymphomas." (PMID 23171647, 2012).
epilepsy (1 paper, 2025). A brain disorder characterized by episodes of abnormally increased neuronal discharge resulting in transient episodes of sensory or motor neurological dysfunction, or psychic dysfunction. "Mutations in PIGU disrupt this process, leading to severe intellectual disability, epilepsy, and brain anomalies." (PMID 40825663, 2025).
cancer (9 papers, 2009 to 2024). A tumor composed of atypical neoplastic, often pleomorphic cells that invade other tissues. "In fact, it has been shown that GPAA1 and PIGU are defined as oncogenes in a variety of cancers." (PMID 39015576, 2024). "NDUFA4L2, CRHBP and PIGU were top genes with monotonic changes of expression across cancer stages that could represent promising targets for therapy." (PMID 31277598, 2019). "Other cancer-related genes located within this SRO include PIGU, E2F1, and DNMT3B." (PMID 19486517, 2009). "The pan-cancer analysis results suggest that the eight hub genes (TXNRD1, TUBG1, SF3B4, PPM1G, PIGU, NDRG1, GRPEL2, and EZH2) were differentially expressed in gastrointestinal tumors." (PMID 36686830, 2022). "PIGT, PIGU, GPAA1, and PIGS are overexpressed in many cancers, whereas PIGK is downregulated." (PMID 34193731, 2021).
tumor (6 papers, 2006 to 2026). "FAM117A expression was markedly decreased in tumor (T) and precancerous (P) tissues compared with normal (N) tissues, whereas PIGU expression was elevated in the T and P groups relative to the N group." (PMID 41542087, 2025). "This suggests that H19 is a key downstream regulatory factor in the anti-tumor process involving high FAM117A expression and low PIGU expression." (PMID 41542087, 2025). "When tumor cells high expressed GPAA1 and PIGU, the fluorescence intensity of CD8 molecules in peripheral infiltrating lymphocytes noticeably decreased, indicating a reduction in the number of CD8+ T cells." (PMID 39015576, 2024).
PIGU also shares sentences with these, for which no sentence is quoted: hepatocellular carcinoma (2 papers); colorectal adenocarcinoma (1); gastrointestinal tumors (1); Hypertension (1); Intellectual disability (1); liver cancer (1); lung carcinoma (1); neurological disorders (1); pancreatic cancer (1); thyroid cancer (1).